GJA1 (gap junction protein alpha 1)
Diseases named in the same sentence as GJA1 in open-access papers (continued):
Sharing a sentence is not in itself a finding about the gene and the disease.
breast cancer (continued). "In recent years, a study confirmed that YTHDF3 promotes breast cancer metastasis by promoting the translation of ST6GALNAC5, GJA1 and EGFR." (PMID 35197112, 2022). "GJA1 is also expressed at lower levels when HER2 status is positive and within the Her2e breast cancer subtype, except in the TCGA dataset." (PMID 29495625, 2018). "Furthermore, during the writing of this paper Giuliano and colleagues showed, using circulating and disseminated tumor cells from breast cancer patient-derived xenograft-bearing mice, that high GJA1 expression could be used to predict distant metastasis-free survival." (PMID 26735887, 2016). "The expression of GJA1/Cx43, GJA3/Cx46 and GJB2/Cx26 and, for the first time, GJA6/Cx30 and GJB1/Cx32 was revealed both in normal human mammary glands and breast carcinomas." (PMID 25383624, 2014). "Some genes associated with cell adhesion were analyzed from this radiation- and estrogen-induced experimental breast cancer model, including E-cadherin gene CDH1, DSC3, GJA1, the Integrin alpha 6 gene ITGA6, the Integrin beta 6 gene ITGB6, the Keratin genes KRT14, KRT16, KRT17, KRT6B, and LAMB3." (PMID 36293530, 2022). "As a m6A reader, YTHDF3 was overexpressed and clinically correlated with breast cancer brain metastases (BCBM), suggesting that YTHDF3 overexpression was indispensable for multiple steps of BCBM through facilitating ST6GALNAC5, GJA1, EGFR, and VEGFA expressions." (PMID 34952600, 2021). "Since Y-276332 (ROCK inhibitor) and H89 were exceptionally potent at stimulating TNT formation, we decided to test these agents in the breast cancer cell line SUM159PT, which displays very few TNTs under basal conditions, despite expressing some Cx43 (but low levels of GJA1-20k)." (PMID 33003486, 2020). "GJA1 mRNA also weakly negatively correlated with DNA copy number, suggesting that Cx43 over-expression in breast cancer is not driven by DNA amplification." (PMID 29495625, 2018). "Interestingly, GJA1 has been described as a tumor-suppressor gene, which is able to reduce migration and proliferation of MCF7 and MDA-MB-231 breast cancer cells." (PMID 26735887, 2016). "We disclosed the expression of five connexin isotypes by confirming the production of GJA1/Cx43, GJA3/Cx46 and GJB2/Cx26 and detecting, for the first time, GJA6/Cx30 and GJB1/Cx32 both in the human pre-menopausal mammary gland and breast carcinomas." (PMID 25383624, 2014). "Based on mRNA expression data, a comprehensive screening for five connexin isotypes, GJA1/Cx43, GJA3/Cx46, GJB2/Cx26, GJA6/Cx30 and GJB1/Cx32 was performed at the protein level in normal pre-menopausal breast glands and in a cohort of cancers representing all grades and major breast cancer subtypes." (PMID 25383624, 2014). "Moreover, YTHDF3 overexpression was clinically correlated with brain metastasis of breast cancer by promoting the translation of crucial brain metastatic genes ST6 N-acetylgalactosaminide alpha-2,6-sialyltransferase 5 (ST6GALNAC5) and gap junction protein alpha 1 (GJA1)." (PMID 38503745, 2024). "Further evidence suggests that Cx43 (GJA1) mRNA expression is negatively correlated with HER2 positivity but a relationship between Cx43 and HER2 in breast cancer is not well defined." (PMID 29312613, 2017). "Therefore, it cannot be excluded that GJA1 mRNA expression can be regulated by ERα or HER2 and that these links could not be captured by expression profiles from breast cancer samples." (PMID 29495625, 2018). "Moreover, Teleki and colleagues suggest that GJA1 and GJA6 could be used as potential positive and negative prognostic markers, respectively, for a clinically relevant stratification of breast cancers." (PMID 26735887, 2016).
glioma (170 papers, 2005 to 2026). A benign or malignant brain and spinal cord tumor that arises from glial cells (astrocytes, oligodendrocytes, ependymal cells). "Importantly, at least part of these N-terminally truncated isoforms can be expressed at the nucleus, as demonstrated in the case of GJA1-20k, in a rat glioma cell line." (PMID 33922534, 2021). "The type 2 tunneling nanotube transcripts (GJA1, GAP43), which overlap with gap junction formations, exhibited a diverse expression in gliomas (GJA1 transcript was significantly overexpressed; however, GAP43 expression was significantly decreased compared to normal brain samples)." (PMID 33096700, 2020). "Specificity of expression for connexin genes in astrocytic cells, GJA1/Cx43, GJB6/Cx30, and GJB2/Cx26, was used to verify expected cells of origin for the glial tumors, oligodendrogliomas, and glioblastomas in REMBRANDT patients on anti-seizure drugs." (PMID 40867621, 2025).
ischemia (108 papers, 2008 to 2025). A hypoperfusion of the BLOOD through an organ or tissue caused by a PATHOLOGIC CONSTRICTION or obstruction of its BLOOD VESSELS, or an absence of BLOOD CIRCULATION. "Loss or reduced expression of Gja1 leads to enlarged infarct size upon induced-ischemia, and the loss of only the C-terminal tail of Cx43 appeared to mediate the damaging effects." (PMID 30577786, 2018). "Whereas dephosphorylation and lateralization of Cx43 at the plasma membrane are often induced by ischemia, overexpression of Gja1-20k helps to maintain Cx43 localization at the intercalated discs in the setting of acute ischemia." (PMID 35860665, 2022). "As a gene therapy or, in the future, as a possible peptide, GJA1-20k has therapeutic potential against anticipated ischemia in the heart, brain, kidneys or other organs subjected to ischemic injury." (PMID 35399255, 2022). "The findings also identify GJA1-20k as a pharmaceutical candidate for protection of organs undergoing anticipated ischemia." (PMID 34608863, 2021). "As a stress-responsive protein, endogenous GJA1-20k is induced by short bouts of ischemia prior to a longer ischemic period." (PMID 34608863, 2021). "Future studies will focus on acute intravenous administration of GJA1-20k peptide in subjects about to undergo anticipated ischemia." (PMID 34608863, 2021). "Recent studies have identified that exogenous GJA1-20k can protect neurons subjected to traumatic brain injury, hearts from ischemia and angiotensin induced hypertrophy." (PMID 34608863, 2021). "The interactions between these pathways, particularly in the context of TNC and GJA1 expression, might dictate the behavior of progenitor cells and their response to injury, including ischemia." (PMID 40003865, 2025). "Interestingly, AAV9-induced GJA1-20k overexpression in heart maintains Cx43 gap junction plaque after acute ischemia injury, while full-length Cx43 overexpression by AAV9 is insufficient to rescue the plaque disruption by ischemia injury." (PMID 35399255, 2022). "An increase in GJA1-20k is observed in brain and heart tissue subject to ischemia." (PMID 32164190, 2020).
glioblastoma (99 papers, 2005 to 2025). The most malignant astrocytic tumor (WHO grade IV). "For instance, GJA1 has been implicated in glioblastoma resistance to temozolomide by modulation of apoptosis and activation of cytoprotective PI3K/Akt pathway." (PMID 41153808, 2025). "This out-group consisted of ABCB1, which encodes the efflux transporter P-glycoprotein, a well-known inducer of multidrug resistance, and GJA1, a gap junction component involved in chemoresistance regulation of glioblastoma cells." (PMID 41153808, 2025). "We also discovered that Cx43 protein inactivation contributed to malignant tumor angiogenesis, although in glioblastoma, GJA1 acted as a tumor invasion promoter." (PMID 37124542, 2023). "This suggests that glioblastomas with high GJA1 expression might have an enhanced ability to pause the cell cycle or activate stress response mechanisms, potentially contributing to chemoresistance, where cancer cells become less sensitive to treatment." (PMID 39680504, 2025). "An association between GJA1 and NEAT1 expression in GBM samples was observed in the analysis of glioblastoma samples, showing a Pearson correlation coefficient of 0.245." (PMID 39453684, 2024). "Connexin 43 (cx43, gap junction protein alpha 1) was of interest as a potential contributor (via gap junctional intercellular communication) to the coordinated responses to IRES inhibition exhibited by both the breast tumor and glioblastoma cells." (PMID 27460074, 2016). "Furthermore, the correlation analysis conducted on samples of glioblastoma revealed a negative correlation between GJA1 levels and miR‐454‐5p expression levels, with a Pearson r value of −0.2577." (PMID 39453684, 2024).
oculodentodigital dysplasia (94 papers, 2009 to 2026). Oculodentodigital dysplasia (ODDD) is characterized by craniofacial, neurologic, limb and ocular abnormalities. "The vast majority of GJA1 mutations cause oculodentodigital dysplasia (ODDD), a disorder that commonly presents with craniofacial abnormalities, digit fusion, and developmental defects of the eyes and teeth." (PMID 35008913, 2022). "The GJA1 gene, corresponding to eQTL rs118074968 (chr6), has been previously implicated in oculodentodigital syndrome." (PMID 35409401, 2022). "Mutations in the CX43-coding gene, GJA1, have been associated with oculodentodigital dysplasia (ODDD), including microphthalmia and other ocular defects such as iris atrophy, glaucoma, strabismus and blindness." (PMID 36499601, 2022). "Oculodentodigital dysplasia (ODDD) is a rare disease caused by a mutation in the gene GJA1 located on chromosome 6 that codes for Cx43." (PMID 36140338, 2022). "They employed wild-type iPSCs cell culture and iPSCs carrying a GJA1 (Cx43) gene mutation from patients suffering from oculodentodigital dysplasia, which were able to differentiate into adipocytes." (PMID 34830025, 2021). "Among them, eighty-nine variants in GJA1 were found to be linked to oculodentodigital dysplasia (ODDD)." (PMID 34360596, 2021). "Various mutations in GJA1 (Cx43) are known to cause oculodentodigital dysplasia (OMIM 164200), and at least one has been linked to primary LE." (PMID 33844116, 2021). "Patients that carry autosomal dominant missense mutations in GJA1 (gene that encodes Cx43) clinically exhibit a developmental disorder known as oculodentodigital dysplasia (ODDD), but typically have fully intact skin." (PMID 33066499, 2020). "Oculodentodigital dysplasia (ODDD) is a rare genetic disease caused by mutations in the GJA1 gene located on chromosome 6, encoding for Cx43." (PMID 33233647, 2020). "During limb and tooth development, Epfn-deficient mice develop similar phenotypes to those of Gja-1 null mice and are used as animal models of ODDD syndrome." (PMID 32258035, 2020). "Mutations in GJA1, the gene encoding Cx43, have been linked to a number of diseases such as the inherited oculodentodigital dysplasia." (PMID 30638447, 2019). "Underscoring its importance for bone development and homeostasis, spontaneous mutations of GJA1 (Cx43 gene) cause rare skeletal disorders, oculodentodigital dysplasia (ODDD) and recessive craniometaphyseal dysplasia." (PMID 29149200, 2017). "Two genes, Gja1 and Cyp27a1 have a striking monogenic association with oculodentodigital dysplasia and cerebrotendinous xanthomatosis respectively, both of which are associated with retinal abnormalities." (PMID 29116131, 2017). "Inherited mutations in GJA1, the gene that encodes for Cx43, have been associated with an autosomal dominant condition called oculodentodigital dysplasia, which predisposes to VT and sudden cardiac death." (PMID 26839915, 2015). "Missense mutations of the GJA1 gene encoding the Cx43 protein cause skeletal malformations called as oculodentodigital dysplasia (ODDD)." (PMID 25933380, 2015). "Mutations in the GJA1 gene encoding Cx43 have been identified in a rare, mostly autosomal dominant syndrome called oculodentodigital dysplasia (ODDD)." (PMID 24133447, 2013). "Point mutations in GJA1, the gene encoding the gap junction protein Cx43, result in the human pleiotropic disorder oculodentodigital dysplasia, which includes skeletal manifestations." (PMID 20338032, 2010). "The proband harbored a de novo hemizygous DMD frameshift variant consistent with Duchenne muscular dystrophy, a paternally inherited heterozygous GJA1 in-frame indel associated with oculodentodigital dysplasia (ODDD), and a novel homozygous FYCO1 nonsense variant causing congenital cataract." (PMID 41853139, 2026). "Pathogenic variants in the GJA1 gene cause oculodentodigital dysplasia." (PMID 38626573, 2024).
oculodentodigital dysplasia (continued). "Cataracts in the eye lens are associated with mutations in Cx46, while mutations in the GJA1 gene which encodes Cx43 lead to a rare autosomal syndrome called oculodentodigital dysplasia (ODD) in which patients display diverse phenotypes such as bone malformations, vision loss, and hypotrichosis." (PMID 36712244, 2022). "Although inherited GJA1 (encoding Cx43) gene mutations most often lead to oculodentodigital dysplasia and related disorders, four variants have been linked to erythrokeratodermia variabilis et progressiva (EKVP), a skin disorder characterized by erythematous and hyperkeratotic lesions." (PMID 35008913, 2022). "We found that control iPSCs, as well as iPSCs derived from oculodentodigital dysplasia patient fibroblasts harboring a GJA1 (Cx43) gene mutation, successfully and efficiently differentiated into LipidTox and perilipin-positive cells, indicating cell differentiation along the adipogenic lineage." (PMID 31514306, 2019). "Interestingly, mutations in yet another connexin member, GJA1, are associated both dominantly and recessively with oculodentodigital dysplasia (ODDD) including the ocular phenotypes of microphtalmia, microcornea, cataract and glaucoma." (PMID 29461512, 2018). "Moreover, mutations in the Cx32 gene (GJB1) are involved in the pathogenesis of X-linked Charcot–Marie–Tooth neuropathy, while mutations in the gene encoding Cx43 (GJA1) result in oculodentodigital dysplasia." (PMID 23596415, 2013). "Mutations in connexin 43, coded for by the GJA1 gene, cause the oculodentodigital dysplasia." (PMID 20805970, 2009). "The GJA1 gene has been associated with oculodentodigital dysplasia, autosomal recessive craniometaphyseal dysplasia, and heart malformations, and may also play a role in the physiology of hearing by participating in the recycling of potassium to the cochlear endolymph and in cell growth inhibition." (PMID 36009466, 2022). "Oculodentodigital dysplasia (ODDD) is an inherited multisystem developmental disorder caused by around 80 distinct mutations in the GJA1 gene encoding for Cx43." (PMID 34072103, 2021). "Human Cx43 mutations are linked to seizures as well, as 30% of patients with oculodentodigital dysplasia (ODDD), a rare genetic condition caused by mutations in the GJA1 gene coding for Cx43 protein, exhibit neurological symptoms including seizures." (PMID 33233647, 2020). "Oculodentodigital dysplasia (ODDD) is an autosomal dominant human disease caused by mutations in GJA-1, which encodes Cx43." (PMID 32258035, 2020). "Mutations in GJA1 can cause oculodentodigital dysplasia (ODDD), characterized by soft tissue fusion of the digits, abnormal craniofacial bone development, small eyes, and loss of tooth enamel." (PMID 30924322, 2019). "Numerous autosomal dominant GJA1 mutations have been reported to cause oculodentodigital dysplasia (ODDD), which is characterized by craniofacial and limb dysmorphisms." (PMID 30577786, 2018). "Mutations in the Cx43 gene (GJA1) are associated with oculodentodigital dysplasia (ODDD), an autosomal dominant syndrome characterized by craniofacial and limb dysmorphology, spastic paraplegia, and neurodegeneration." (PMID 28494020, 2017). "For example, in an autosomal dominant disorder termed oculodentodigital dysplasia (ODDD), skin manifestations are associated with over 70 mutations in the Cx43 gene (GJA1)." (PMID 27999549, 2016). "Early in the new millennium, germline mutations in the GJA1 gene encoding Cx43 were found to be causal of oculodentodigital dysplasia (ODDD)." (PMID 27230612, 2016). "The syndrome oculodentodigital dysplasia (ODDD), characterized by abnormalities in craniofacial elements, limbs and dentition, has been linked to missense mutations in the GJA1 gene locus in humans." (PMID 24533114, 2014). "Oculodentodigital dysplasia (ODDD), a rare genetic disorder inherited in an autosomal dominant pattern, is also caused by GJA1 mutations." (PMID 38827992, 2024).
oculodentodigital dysplasia (continued). "GJA1 is the causative gene for oculodentodigital dysplasia (ODDD)." (PMID 38221519, 2024). "Connexin 43 (GJA1, OMIM:121014) is located on chromosome 6 (6q21-q23.2) of the human genome and has been implicated in a number of diseases but mainly in oculodentodigital dysplasia with pleiotropic phenotypes." (PMID 33126609, 2020). "Oculodentodigital dysplasia (ODDD) is a rare disorder with pleiotropic effects involving multiple body systems, caused by mutations in the gap junction protein alpha 1 (GJA1) gene." (PMID 31347275, 2019). "Oculodentodigital syndrome or oculodentodigital dysplasia (ODDD, OMIM #164200) is a mostly autosomal dominant disease caused by mutations in the GJA1 gene which is located on chromosome 6 (q21-q23.2)." (PMID 24133447, 2013). "They display many similarities with the phenotypes reported from human oculodentodigital dysplasia (ODDD), an autosomal dominant disease caused by any one of over 60 mutations in the gene GJA1 encoding Cx43." (PMID 21858092, 2011). "Oculodentodigital dysplasia (ODDD) is a rare, autosomal dominant disorder caused by mutations in the gap junction protein alpha-1 (GJA1) gene encoding the gap-junction hemichannel connexin 43 (Cx43)." (PMID 35008700, 2021). "This is the case of oculodentodigital dysplasia (ODDD), an autosomal dominant disease characterized by developmental abnormalities in limbs, teeth, face and eyes, due to mutations in the GJA1 gene, encoding Cx43." (PMID 33922534, 2021). "In fact, it was initially thought that mutations of the Cx43 gene, GJA1, would be lethal, given its importance for cardiac function; however autosomal dominant mutations in GJA1 were recently linked to oculodentodigital dysplasia (ODDD), a developmental disorder with some myocardial implications." (PMID 33013490, 2020). "The mutation in the human GJA1 gene encoding CX43 is known to be responsible for an extremely rare disease, oculodentodigital dysplasia (ODDD), manifested by small eyes, underdeveloped teeth, and malformation of fingers." (PMID 28271062, 2017). "Cx43 is widely found in the human anatomy, and more than 80 different mutations in the gene encoding Cx43 (GJA1) are associated with the pleiotropic developmental disorder known as oculodentodigital dysplasia (ODDD)." (PMID 31514306, 2019).